CDH1 (cadherin 1)
Diseases named in the same sentence as CDH1 in open-access papers (continued):
Sharing a sentence is not in itself a finding about the gene and the disease.
tubular carcinoma (6 papers, 2018 to 2025). "An amino acid deletion (p.Glu761*) in the CDH1 protein was found only in several types of MGT tissues (lipoma, tubulopapillary carcinoma, tubular carcinoma)." (PMID 41168812, 2025).
acute pancreatitis (5 papers, 2009 to 2023). An acute inflammatory process that leads to necrosis of the pancreatic parenchyma. "An artificial neural network (ANN) model consisting of Fabp5, TLR4, Actb and Cdh1 was useful in predicting severe acute pancreatitis." (PMID 38188879, 2023). "Gene expression of Cdh1 was decreased in patients with acute pancreatitis when compared to healthy volunteers." (PMID 38188879, 2023). "Rela, Actb, Cdh1, and Vcl were hub genes of acute pancreatitis." (PMID 38188879, 2023).
co-infection (5 papers, 2012 to 2025).
colon adenoma (5 papers, 1997 to 2018). An adenoma that arises from the colon. "Recently, expression of conditional, mutated and stabilised β-catenin in the mouse failed to generate a significant colonic adenoma phenotype unless combined with a Cdh1 heterozygote allele, suggesting that the adhesion complex sequestration of mutated β-catenin limited its nuclear translocation." (PMID 27566565, 2016).
colorectal adenoma (5 papers, 2012 to 2022). An adenoma that arises from the colon or rectum. "On the transcriptional level, we observed a significant correlation between SNAI1/Snail1 expression and CDH1/E-cadherin loss in colorectal adenomas." (PMID 23029563, 2012). "In conclusion, our hypothesis generating study revealed SNAI1 expression as well as combined SNAI1/TWIST expression to be associated with decreased expression of CDH1 in colorectal adenomas." (PMID 23029563, 2012). "CDH1 expression was significantly reduced in colorectal adenomas compared to normal colonic mucosa (p = 0.035, Mann-Whitney-U test)." (PMID 23029563, 2012). "The colorectal adenomas with preserved E-cadherin staining showed a significantly higher amount of CDH1 mRNA in the qRT-PCR, compared with colorectal adenomas with reduced E-cadherin immunoreactivity (p = 0.003, Mann-Whitney-U test)." (PMID 23029563, 2012). "Strikingly, mRNA expression of SNAI1 was significantly correlated with decreased levels of CDH1 mRNA in colorectal adenomas, suggesting an “active” CDH1 suppression by the transcription factor SNAI1." (PMID 23029563, 2012). "As in our current study on colorectal adenoma tissue, they observed in diffuse gastric cancer that increased SNAI1 mRNA expression was associated with down-regulation of CDH1 mRNA." (PMID 23029563, 2012). "All 17 of the CDH2 positive colorectal adenomas were also positive for CDH1 mRNA." (PMID 23029563, 2012). "In the 32 colorectal adenomas, which were positive for SNAI1 mRNA, the amount of CDH1 mRNA was significantly lower (p = 0.004, Mann-Whitney-U test), compared to the amount in colorectal adenomas without SNAI1 mRNA expression." (PMID 23029563, 2012). "Colorectal adenomas positive for TWIST1 mRNA also showed a lower amount of CDH1 mRNA - the correlation was not significant (p = 0.29, Mann-Whitney-U test)." (PMID 23029563, 2012). "When comparing the amount of CDH1 mRNA in colorectal adenomas with or without SNAI1 expression, we found a significant difference." (PMID 23029563, 2012). "Even though it was often proposed that N- and E-cadherin have contrary functions in cancer progression, we could not find a significant inverse correlation between CDH1 and CDH2 mRNA expression in colorectal adenomas or carcinomas." (PMID 23029563, 2012).
epilepsy (5 papers, 2019 to 2024). A brain disorder characterized by episodes of abnormally increased neuronal discharge resulting in transient episodes of sensory or motor neurological dysfunction, or psychic dysfunction. "For example, a mutation was found in CDH1 that causes neurological defects, e.g., microencephaly and epilepsy." (PMID 34109183, 2021). "Germline mutations with pathogenic or likely pathogenic effects at glycosylation sites are associated with cardiomyopathies (MYH7), cancer predisposition (CDH1), epilepsy (SCN1B), and others." (PMID 33834021, 2021). "Here, we describe a de novo Cdh1 mutation (p.Asp187Gly) in a 4‐year‐old boy with prenatal microcephaly, psychomotor retardation, and epilepsy." (PMID 31318984, 2019). "Thus, the loss of Cdh1 may alter the excitatory to inhibitory balance, hence explaining the occurrence of epilepsy in the patient herein identified." (PMID 31318984, 2019). "Here, we describe a de novo missense mutation (c.560A>G) in the human Fzr1 gene that predicts an aspartate‐to‐glycine substitution (p.Asp187Gly) in the Cdh1 protein, which results in prenatal microcephaly, psychomotor retardation, and severe epilepsy." (PMID 31318984, 2019). "Thus, Cdh1 Asp187Gly mutation is herein identified as a novel cause of APC/C‐Cdh1 inactivation triggering prenatal microcephaly, psychomotor retardation, and severe epilepsy in human." (PMID 31318984, 2019).
liver cirrhosis (5 papers, 2014 to 2022). "Our results showed that the expression of cell adhesion molecules, such as CDH1, PECAM1, SELL and CAV1, which are canonical molecules in cell adhesion, was evidently changed in liver cirrhosis." (PMID 34434654, 2021).
oncocytoma (5 papers, 2007 to 2024). "CDH1 methylation is significantly higher in ccRCC than in chRCC or oncocytoma, important discrimination due to the benign nature of oncocytoma." (PMID 33922974, 2021). "CDH1 hypermethylation levels were significantly higher in ccRCC compared to chRCC and oncocytoma (p = 0.00016 and p = 0.0034, respectively), whereas PTGS2 methylation levels were significantly higher in ccRCC compared to pRCC (p = 0.004)." (PMID 17645803, 2007).
parasitemia (5 papers, 2015 to 2026). "However, the course of parasitemia as well as the leukocyte count and cellular composition was similar in the peritoneum of Cdh1Δ and Cdh1F/F infected mice, ruling out an important role of E-cadherin expression in macrophages during cysticercosis." (PMID 26226941, 2015).
rhabdomyosarcoma (5 papers, 2015 to 2023). A rare aggressive malignant mesenchymal neoplasm arising from skeletal muscle. "Additionally, in context to rhabdomyosarcoma cases, upregulations of CDH1 (epithelial marker), SLUG (inducer of EMT), and MMP9 (matrix-modifying enzyme) are reported." (PMID 37503316, 2023).
airway hyperresponsiveness (4 papers, 2020 to 2026). "E‐cadherin and occludin are known to be downregulated in asthmatics, and the genes for E‐cadherin and protocadherin‐1 have been associated with airway hyperresponsiveness." (PMID 32196653, 2020).
allergic asthma (4 papers, 2015 to 2025). A asthma with a basis in a pathological type I hypersensitivity reaction. "In a mouse model of allergic asthma, acute HDM exposure significantly increased TGFβ1 protein in the BAL fluid, decreased expression of CDH1 and occludin in the airway epithelium, and increased expression of VIM, αSMA and pro-collagen 1 in the mesenchyme." (PMID 36230980, 2022).
Anxiety (4 papers, 2017 to 2025). Intense feelings of nervousness, tension, or panic often arise in response to interpersonal stresses. "Anxiety specifically related to the diagnosis of CDH1 P/LP variant was self-reported in four patients." (PMID 37903316, 2024). "Several perceived benefits of PGT were described by participants, with the most common responses reflecting the ability to eliminate mutations known to be pathogenic (e.g., CDH1) and to minimize suffering or anxiety experienced by themselves and their children." (PMID 36056367, 2022). "Although our preliminary behavioral studies suggest alleviation of learning deficits and no alteration of anxiety by overexpression of Cdh1 in isoflurane-treated rats, more cohorts and tests are needed to confirm our observations reported here." (PMID 29218001, 2017).
atherosclerosis (4 papers, 2011 to 2023). A disease characterized by the build-up of fatty material and calcium deposition in the arterial wall resulting in partial or complete occlusion of the arterial lumen. "CDH1 and CDH5 expressions are increased by C. pneumoniae infection of human brain microvascular endothelial cells, contributing to vascular permeability changes and atherosclerosis." (PMID 22254144, 2011).
ependymoma (4 papers, 2019 to 2024). A WHO grade II, slow growing tumor of children and young adults, usually located intraventricularly. "Similarly, a comparative transcriptomic analysis of grade 2 ependymomas (intermediate risk) and grade 3 ependymomas (high risk) showed that in the latter, there is a decrease in the regulation of CDH-1 (E-cadherin) and the activation of this machinery of destruction." (PMID 36291193, 2022).
Fibroadenoma (4 papers, 2016 to 2021). A benign tumor of the breast characterized by the presence of stromal and epithelial elements. "However, we observed that one common characteristic of SGSM2 and CDH1 is that both are highly expressed in fibroadenoma (*P = 0.002 and D, *P = 0.038)." (PMID 30744493, 2019).
gastric disease (4 papers, 2016 to 2025). "This study investigates the role of CDH1 gene single nucleotide polymorphisms (SNPs), mRNA transcription levels, and E-cadherin protein localization in Helicobacter pylori (Hp)-associated gastric diseases and their contribution to gastric mucosal carcinogenesis." (PMID 40416864, 2025).
hepatoblastoma (4 papers, 2013 to 2025). Hepatoblastoma (HB) is a malignant hepatic tumor and is the most common pediatric liver cancer. "As a result, aberrant DNA methylation at the APC, CDH1, MT1G, RASSF1A and SOCS1 promoters were reported in hepatoblastoma." (PMID 36212481, 2022).
hereditary nonpolyposis colorectal cancer (4 papers, 2013 to 2023). "Risk factors include bacterial (Helicobacter pylori) and viral (Epstein-Barr virus, EBV) agents, as well as rare hereditary mutations in the CDH1 gene or in Mismatch Repair genes involved in the hereditary nonpolyposis colorectal cancer (HNPCC) or Lynch syndrome." (PMID 33671606, 2021).
hereditary tumor syndromes (4 papers, 2013 to 2025). "Other frameshift variants in the nearby region have been reported in individuals with hereditary cancer-predisposing syndrome, and Familial cancer of breast, loss-of-function of CDH1 is a well-established mechanism leading to the disorder." (PMID 39148954, 2024). "The CDH1 gene, which encodes for E-cadherin, functions as a tumor suppressor gene and CDH1 germline mutations are associated with a hereditary tumor syndrome." (PMID 24023670, 2013). "As already described in other hereditary tumor syndromes, type and location of a germline PV on the CDH1 gene may influence penetrance." (PMID 33322525, 2020).
liver disease (4 papers, 2016 to 2024). "By training random forest models, a biomarker panel comprising KNG1, F11, KLKB1, CAPNS1, CDH1, CPN2, NME2, was identified by feature selection for liver disease detection." (PMID 39207047, 2024).
microcephaly (4 papers, 2019 to 2023). A congenital or acquired developmental disorder in which the circumference of the head is smaller than normal for the person's age and sex. "We previously found that the anaphase promoting complex/cyclosome (APC/C) inactivation, by deletion of its activator Cdh1, promotes microcephaly in mouse." (PMID 31318984, 2019).
pterygium (4 papers, 2010 to 2025). A wedge-shaped fibrovascular lesion arising from the bulbar conjunctiva and extending to the cornea. "Additionally, CLDN1 mRNA expression was significantly reduced in pterygium corneal epithelial samples (p = 0.023), and CDH1 mRNA expression was significantly lower in EBMD (p = 0.021) and pterygium corneal epithelial samples (p = 0.003) than in controls." (PMID 40094891, 2025).
Q fever (4 papers, 2019 to 2023). A bacterial infection caused by Coxiella burnetii. "Herein, we evidenced for the first time that sE-cad is released from cell membrane in patients with Q fever, and that C. burnetii infection modulates the expression of the CDH-1/E-cadherin and CTNNB1/β-catenin genes and the cell-surface expression of E-cad on monocytes during Q fever." (PMID 31293984, 2019).
chronic lung disease (3 papers, 2020 to 2025). According to the definitions of the American and British Thoracic Societies, including pulmonary functional tests, X-rays, and CT scans for items such as fibrosis, bronchiectasis, bullae, emphysema, nodular or lymphomatous abnormalities. "Notably, the loss of CDH1, the gene encoding for E-cadherin, has been causally associated with chronic lung disease." (PMID 40862704, 2025).
chronic lymphocytic leukemia (3 papers, 2013 to 2020). "Further analysis showed a low histone acetylating level of CDH1 exon 11 in chronic lymphocytic leukemia cells." (PMID 26674321, 2015).
emphysema (3 papers, 2014 to 2022). "As a final example, the “causal” relationship suggested for CDH1 (E-cadherin) for both emphysema and FEV1% predicted is also intriguing at a mechanistic level." (PMID 27532455, 2016). "In addition, intercellular adhesion molecule 1 (ICAM1), macrophage inhibitory protein 3a (CCL20) and cadherin 1 (CDH1) were negatively associated with emphysema severity." (PMID 25306249, 2014). "Other biomarkers that were associated with emphysema include CDH1, CDH 13 and SERPINA7, but were not available for validation in the TESRA study." (PMID 25306249, 2014). "CDH1 was negatively correlated with radiologic emphysema across all emphysema outcome measurements." (PMID 25306249, 2014). "The study confirms a previously identified association between radiologic emphysema and sRAGE, builds on data suggesting a role for ICAM1 as a biomarker, in addition to discovering previously not identified biomarkers associated with emphysema such as CCL20, cadherin 1, cadherin 13 and SERPINA7." (PMID 25306249, 2014).
endometrial tumors (3 papers, 2016 to 2025). "E-cadherin expression loss has been described in gynecological neoplasias, and CDH1 silencing by promoter methylation has been detected in both cervical and endometrial tumors." (PMID 27349965, 2016). "Her endometrial tumor harbored a somatic MSH6 mutation without a detectable germline mutation in any of the mismatch repair genes; however, she was found to have a pathogenic germline CDH1 mutation (c.715G > A (p.Gly239Arg) on NGS." (PMID 40242369, 2025).
endometrioid tumor (3 papers, 2019 to 2021). A benign, borderline, or malignant epithelial tumor of the female reproductive system characterized by the presence of glands and/or cysts lined by neoplastic cells that resemble endometrial cells. "Reduced expression of CDH1 and KRT18 was significantly associated with high-grade tumors and non-endometrioid tumor histology, while increased expression CTSB, CDH2 and ZEB1 could be observed in serous tumors." (PMID 34936030, 2021).
gastric signet ring cell adenocarcinoma (3 papers, 2016 to 2023). "The association with genetic causes is not well known, with only a few cases reported in which mutations occurred in the CDH1 (Cadherin 1) gene when appendiceal signet-ring cell adenocarcinoma was associated with gastric signet-ring cell adenocarcinoma, and also in the KRAS and GNAS genes." (PMID 37568688, 2023).
Hearing Loss (3 papers, 2019 to 2025). "Two VCEPs, Hearing Loss (HL) and CDH1, detailed their approach for estimating the predictive power of assays to determine which assays should be approved for use as PS3/BS3 evidence." (PMID 31783775, 2019). "CDH1 has been widely reported to be associated with hearing loss." (PMID 34912812, 2021). "The protein–protein interaction network analysis identified prominent interaction characteristics among neighboring genes of tinnitus-associated loci (RUNX2, TGFB2, CDH1, and DEFB family) and hearing-loss-associated loci (CDH1, PRR19, and MAGOHB)." (PMID 40362371, 2025). "Finally, the PPI networks identified in this study, particularly those involving RUNX2, TGFB2, and CDH1, may serve as the foundation for novel therapeutic approaches aimed at restoring auditory function in patients who have already experienced radiotherapy-induced hearing impairment." (PMID 40362371, 2025).
hereditary gastric cancer (3 papers, 2014 to 2023). Hereditary gastric cancer refers to the occurrence of gastric cancer in a familial context and is described as two or more cases of gastric cancer in first or second degree relatives with at least one case diagnosed before the age of 50. "Hereditary gastric cancer of the diffuse type due to a missense mutation of the CDH1 gene coding for E-cadherin is a more prevalent type of genetic gastric cancer." (PMID 37941554, 2023). "Hereditary stomach cancer is associated with mutations in the CDH1 gene and it is also manifested in Lynch (hereditary nonpolyposis colorectal cancer) syndrome related to mutations in mismatch repair genes." (PMID 34503195, 2021).
hypospadias (3 papers, 2023 to 2024). Hypospadias is the displacement of the urethral meatus on the ventrum of the penis. "Several of these MeSH terms are associated with TF (transferrin), EGF (epidermal growth factor), MMP14 (Matrix metallopeptidase 14), CDH1 (Cadherin 1), and F13A1 (Coagulation factor XIII A chain) genes, related to CLJ and hypospadias." (PMID 37238140, 2023).
influenza (3 papers, 2013 to 2021). An acute viral infection of the respiratory tract, occurring in isolated cases, in epidemics, or in pandemics; it is caused by serologically different strains of viruses (influenzaviruses) designated A, B, and C, has a 3-day incubation period, and usually lasts for 3 to 10 days. "Evidence exists for an association between influenza infection and the subsequent differential regulation of several genes in our list, such as cadherin 1, ATPase, mago-nashi homolog, proteasome 26S subunit, and ribosomal protein L35a." (PMID 23521892, 2013).
intestinal cancer (3 papers, 2019 to 2022). "While the germline alterations in certain susceptibility genes were also detected in the bowel cancer samples including FANCD2, CDH1, FLCN, MEN1, SDHB, and SLX4, which have been rarely reported in the Chinese population." (PMID 35154239, 2021).
malaria (3 papers, 2012 to 2021). Malaria is a serious and sometimes fatal disease caused by a parasite that commonly infects a certain type of mosquito which feeds on humans. "We studied the function of the single homologue of CDC20/CDH1 expressed in the rodent malaria parasite, Plasmodium berghei." (PMID 22383885, 2012). "Chloroquine may inhibit CDH1-null cells at concentrations routinely achieved during malaria treatments." (PMID 35008266, 2021).
myopia (3 papers, 2021 to 2025). "Cadherin associated pathways have also been shown to be pathological during the initiation and progression of myopia, consistent with our prediction on the specific role of CDH1 using both methods." (PMID 40110040, 2025).